MYC (MYC proto-oncogene, bHLH transcription factor)
Diseases named in the same sentence as MYC in open-access papers (continued):
Sharing a sentence is not in itself a finding about the gene and the disease.
cancer (continued). "This study investigated how the recombinant Escherichia coli Lon protease (rLon), which targets MYC in human cells, inhibits MYC over-activation in models of infection and cancer." (PMID 40000737, 2025). "When this balance is altered, MYC becomes a potent oncogene that promotes cancer progression by upregulating genes involved in cell cycle regulation, metabolism, and survival." (PMID 40076599, 2025). "The activation of MYC induces cancer cells to preferentially utilize glycolytic metabolism rather than oxidative phosphorylation, even under normoxic conditions, a phenomenon known as the Warburg effect." (PMID 40290126, 2025). "The upregulation of MYC expression observed in many cancer cells induces ornithine decarboxylase expression, which enhances polyamine synthesis." (PMID 40564899, 2025). "Finaly, given that MYC induces a glycolytic phenotype in cancer cells, exploring the synthetic lethality of ncRNAs that directly affect metabolism is a promising approach." (PMID 40126351, 2025). "In summary, our study identifies PA2G4 as a novel and critical regulator of MYC protein stability, establishing it as a promising therapeutic target in MYC-driven cancers." (PMID 41002386, 2025). "This makes it essential to develop strategies for MYC inhibition, particularly in paediatric cancers." (PMID 41198629, 2025). "c-MYC can regulate the expression and synthesis of various immune interacting proteins, receptors, and ligands, enabling cancer cells to avoid recognition and elimination by the immune defense mechanisms." (PMID 40711670, 2025). "In inducible MYC models, toggling MYC expression in cancer cells directly altered epichaperome levels: MYC overexpression in epichaperome-low cells triggered assembly, while MYC withdrawal in epichaperome-high cells led to their disassembly." (PMID 40877054, 2025). "Targeting this interaction—either by disrupting EWS-FLI-1 activity or inhibiting MYC-dependent pathways—offers a promising avenue for therapeutic intervention in this aggressive cancer." (PMID 40076599, 2025). "This provides strong evidence that FFX can regulate mTOR and MYC signaling in cancer cells via activation of the AKT pathway." (PMID 40027648, 2025). "TEAD is also involved in regulation of MYC, one of the most commonly activated oncoproteins in cancer." (PMID 41347094, 2025). "The MYC oncogene is one of the most frequently dysregulated drivers in human cancer, promoting uncontrolled proliferation, altered metabolism, immune evasion, and other hallmark features of malignancy." (PMID 41025936, 2025). "Research has demonstrated that the human TSPAN8 protein regulates MYC expression by binding to its promoter, enhancing STAT3’s chromatin occupancy, and influencing cancer-related gene transcription, including MYC." (PMID 40862719, 2025). "Signalling pathways including MYC, mTORC1, Mitotic spindle, G2M, and E2F pathways are enriched in most cancers." (PMID 40111059, 2025). "Their selective CDK9 degrader led to greater downregulation of MYC and anti-apoptotic proteins, resulting in enhanced cancer cell death." (PMID 40574056, 2025). "Targeting this regulatory system with miRNA-based approaches, such as sponge constructs, represents a promising but underexplored strategy to simultaneously destabilize MYC dosage compensation and impair cancer cell survival." (PMID 40940795, 2025). "Mutations in subunits of the SWI/SNF complex promote pro-tumorigenic functions, enhancing the activity of oncogenic TFs like MYC and E2F, which drive cancer progression." (PMID 40016470, 2025). "Plasmocytoma Variant Translocation 1 (PVT1), a long non-coding RNA (lncRNA) adjacent to MYC on chromosome 8 is a rearrangement hotspot in many MYC+ cancers." (PMID 40027648, 2025). "In MRT and other SNF5-deficient cancers, the activation of MYC target gene signatures is observed, which is thought to be due to the loss of SNF5-mediated inhibition of MYC functionality." (PMID 40647552, 2025).
cancer (continued). "Based on the ALAN quantitative outputs, RSPO2 behaved similarly to EMT-related genes and FGFR1/2, but exhibited opposing behavior with AR regulatory genes and MYC, a pan-cancer oncogene." (PMID 40711886, 2025). "Microscopic analysis of GNE/BMS-treated cells showed that KRASG12V/MYC cancer cells reacted with the formation of slender cell extensions and an increased size." (PMID 40550880, 2025). "Recent preclinical data highlight that concurrent inhibition of MYC sensitizes cancer cells to chemotherapeutic agents, reducing chemotherapy doses required and potentially decreasing systemic toxicity." (PMID 40365020, 2025). "Beyond these, p62 also correlated positively with UPR and MYC target gene sets across multiple cancers, supporting its broader role in promoting metabolic plasticity and proteostatic stress adaptation." (PMID 41291343, 2025). "Concurrently, it also significantly downregulated DNA repair, mTORC1 signaling, MYC targets, cell cycle, and other cancer-related pathways." (PMID 41429768, 2025). "The up-regulated pathways primarily related to cancer cell proliferation included the E2F, MYC, and G2M signaling pathways." (PMID 40568194, 2025). "MYC is a well-known upstream regulator of Ribosis that enhances ribosomal DNA transcription and ribosomal protein production, thereby promoting cancer cell growth." (PMID 40642093, 2025). "Recent evidence suggests the existence of a multifaceted regulatory loop between TERT, NF-κB p65, and MYC in B-cell malignancies that contributes to cancer progression." (PMID 40227701, 2025). "In stem/TA-like cells (cancer cells), we observed a shift in isoform usage, with reduced MYC-206 and increased MYC-202 deployment." (PMID 40702779, 2025). "Mechanistic investigations indicated that FAM111B facilitated malignant progression of cancer cells by modulating MYC." (PMID 40781291, 2025). "Despite these historical difficulties, a small number of promising inhibitors for MYC-dependent cancers have recently been described, some of which have entered clinical trials (e.g., OMO-103, MRT-2359, WBC100)." (PMID 39875774, 2025). "Theoretically, PROTACs/molecular glues should be able to degrade and eliminate any protein target, thus offering the potential to target cancer-driver proteins that historically were difficult to inhibit such as MYC." (PMID 39875774, 2025). "An interaction between HSF1 and MYC was also detected in OVCAR3 cells that have MYC and HSF1 wild-type (WT) genes, consistent with previous work indicating an interaction between HSF1 and MYC in non-cancer cells." (PMID 39831777, 2025). "A recent study has shown that MYC binds to promoters, invades distal enhancers, and co-occupies them with cancer-type-specific TFs, such as ER and STAT3." (PMID 40032852, 2025). "Analysis of both MYC and HSF1 copy numbers indicated that MYC had amplification in 11% (1,132/9,950) of human cancers, whereas HSF1 was amplified in 8% (840/9,950) of cancers with an overlap in a substantial number of patients." (PMID 39831777, 2025). "MYC overexpression is a well-established cancer vulnerability, yet direct therapeutic targeting of Myc remains a challenge." (PMID 41173942, 2025). "The BET family is composed by BRD2, BRD3, BRD4, and BRDT, and plays important roles in cancer by directly regulating the expression of cancer-related genes such as MYC, and the transcription factor NF-κB." (PMID 41551874, 2025). "MYC is a proto-oncogene located on chromosome 8q24, playing a critical role in the development and progression of cancer, as the MYC protein has a strong influence on biological processes such as cellular metabolism, proliferation and apoptosis." (PMID 40869163, 2025). "First, lactate acts as a metabolic signal, activating cancer-promoting genes like MYC via histone lactylation modification and enhancing DNA repair gene expression, leading to chemoradiotherapy resistance." (PMID 40672391, 2025).
cancer (continued). "MYC proteins are potent oncoproteins that drive tumorigenesis in a wide range of cancers, making it critical to understand their oncogenic functions and underlying mechanisms." (PMID 40488968, 2025). "Based on this model, we discuss potential therapeutic strategies targeting MYC‐dependent stress responses, offering new avenues for cancer treatment and highlighting the complexity of MYC‐driven oncogenesis." (PMID 40488968, 2025). "It is demonstrated that c-MYC represses immune cell infiltration into tumors by inhibiting IFN/STING signaling in a cancer cell-intrinsic manner, particularly in TNBC cells." (PMID 40333779, 2025). "The oncogene MYC supports cancer cell proliferation and survival by concurrently inducing multiple anabolic processes." (PMID 39852139, 2025). "Although the role of MYC in regeneration and cancer is well established, our work expands these studies further by providing a function to a large upstream super-enhancer region of MYC." (PMID 40180576, 2025). "This process is tightly regulated by the PI3K/RAS/MYC oncogenic network, which is frequently deregulated in many cancers." (PMID 40805230, 2025). "When LINC00901 is upregulated, IGF2BP2 is also upregulated, stabilizing MYC mRNA, which in turn upregulates MYC and promotes cancer progression." (PMID 40448344, 2025). "While FBXL16 is an oncoprotein that promotes cancer cell growth and migration by increasing c-MYC stability, Orientia evolved as an obligate intracellular microbe to stabilize c-MYC and extend the life of its host cell." (PMID 39976440, 2025). "BET proteins are essential for the expression of oncogenes such as MYC, and their inhibition has shown efficacy in several cancers." (PMID 39851497, 2025). "c-MYC, the major oncogene activated in over 50% of human cancers, plays a significant role in this context." (PMID 39949372, 2025). "Among these, MYC is particularly noteworthy, as aberrant c-MYC expression is observed in approximately 70% of human cancers." (PMID 40040695, 2025). "For example, MYC is activated by genetic, epigenetic, or post-translational mechanisms in most cancers, and it can inhibit the immune response against these cancers in various ways." (PMID 40777041, 2025). "CDK9 inhibitors such as KB-0742 have recently entered clinical trials (e.g., Phase I/II trial NCT04718675), with preliminary pharmacodynamic data showing effective reduction of MYC expression in preclinical cancer models." (PMID 40365020, 2025). "BRD4 is believed to be a promising anti-cancer drug target due to its strong positive effects on the expression of the transcription factor MYC, which is a well-known oncogenic master regulator and a driver of colon tumorigenesis." (PMID 41311847, 2025). "The deregulation of the MYC oncogene family has been found in many types of cancer and is relevant to a poor prognosis." (PMID 40465781, 2025). "In CRC, superenhancers are enriched not only for BRD4 but also for other proteins, such as the coactivator Mediator, which cooperates with BRD4 in sustaining the expression of cancer-acquired superenhancer genes (e.g., MYC)." (PMID 41311847, 2025). "Based on the notion of “transcriptional addiction,” targeting transcription regulators, including CDK7, has emerged as a powerful strategy to attenuate cancer dependency, particularly in cancers that rely on SE-driven genes (e.g., MYC, RUNX2, SOX2, SOX9)." (PMID 39800748, 2025). "MYC is a master regulator of malignant growth, but excess MYC protein levels prime both normal and cancer cells for apoptosis." (PMID 39857943, 2025). "Hits that scored as selective dependencies in the dual ARID1 paralog-deficient setting included POLA2, RAPTOR, and NUP50, corresponding to pathways such as MYC targets, G2/M checkpoint, DNA replication and undifferentiated cancer signatures." (PMID 41279405, 2025).
cancer (continued). "We also examine how MYC‐induced transcriptional and replicative stress generates potentially immunogenic nucleic acid species while simultaneously helping cancer cells evade host immune recognition." (PMID 40488968, 2025). "The FAK amplification partially overlaps with MYC oncogene and is consistent with their proximity on chromatin 8q24 arm, but the frequency is relatively low compared to other cancer types." (PMID 40959971, 2025). "In conclusion, we established that compromising mitochondrial metabolism, particularly complex I function, represents a key vulnerability factor in MYC-inhibited cancers." (PMID 40668928, 2025). "Oncogenic mutations like KRAS, MYC, AKT can increase electron flow through the ETC, enhancing ROS production and creating a feedback loop that sustains the cancer phenotype." (PMID 40734168, 2025). "The significant enrichment of five cancer-related hallmark pathways were revealed in the high-risk group through GSEA, including DNA repair, E2F targets, MYC targets V1, PI3K/AKT/MTOR signaling, and reactive oxygen species pathway (FDR < 0.05)." (PMID 41200185, 2025). "The transcription factor MYC serves as a pivotal driver of oncogenic signaling across multiple cancer types, including NSCLC." (PMID 40943063, 2025). "Similar dual regulation of pro- and anti-apoptotic genes was observed in BEAS-2B cells infected with Spn reference strain D39 for 16 hours, mirroring patterns reported in MYC-driven cancer biology." (PMID 40475528, 2025). "Given its widespread involvement in cancer, MYC has emerged as an attractive, albeit challenging, target for cancer therapy." (PMID 40227591, 2025). "Our study demonstrated that squamocin effectively suppresses the functions of the EZH2/MYC axis across multiple cancer types." (PMID 39823459, 2025). "We found that the low-prognostic model score group was positively correlated with many cancer super-pathways, including MYC targets V2, PI3K AKT MTOR signaling, and DNA repair." (PMID 40661777, 2025). "Since MYC encodes transcription factors with oncogenic roles in many cancers, we further explored the underlying mechanisms of helenalin, BHM, and BHG on MYC signaling." (PMID 40282497, 2025). "Taken together, reduced CCAT1 expression has the potential to reduce the transcription of MYC gene, thereby having the potential to impair NK cell functions in cancer patients." (PMID 40781182, 2025). "MYC is dysregulated in most human cancers and is a DNA damage response (DDR) modulator capable of both promoting genomic instability and enhancing DNA repair." (PMID 41273720, 2025). "This renders CSCs particularly sensitive to mitochondrial targeting (i.e., metformin), whereas differentiated cancer cells, characterized by increased MYC expression and a glycolytic phenotype, were mostly resistant to metformin." (PMID 40607925, 2025). "While all three pathways have documented roles in cancer biology, their potential to directly regulate cancer splicing programs alongside MYC remains unvalidated." (PMID 41101775, 2025). "These outcomes represent a pivotal breakthrough, definitively demonstrating the feasibility and potential efficacy of direct MYC inhibition in human cancers." (PMID 40365020, 2025). "In this regard, the oncogene c-Myc, a member of the MYC transcription factor family, is abnormally expressed in up to 70% of human cancers." (PMID 40429805, 2025). "Regarding non-AUG initiation events, there are numerous examples of N-terminally extended proteoforms for genes involved in cancer progression, one of the earliest such discoveries was made for the c-MYC oncogene in 1988." (PMID 40276932, 2025). "In this study, we explore how a major oncogenic driver with deep ties to cancer—MYC—influences the SCCOHT transcriptome." (PMID 40647552, 2025). "Studies of the key factors and mechanisms that regulate MYC (e.g., transcription, translation, stability, and activation) will provide new opportunities to treat cancer with targeted therapy." (PMID 40290126, 2025).
cancer (continued). "Emerging evidence suggests that aberrant PUS7 activity contributes to disease states such as cancer, where it promotes oncogenic pathways including MYC/MYCN signaling, metabolic reprogramming, and cell proliferation." (PMID 40940790, 2025). "Taken together, these findings suggest that resistance mechanisms conserved between C. auris and human cancer involve MYC, its downstream regulatory processes, and drug efflux pumps." (PMID 41019980, 2025). "High levels of c-MYC expression correlate with poor prognosis and increased resistance to chemotherapeutic agents in various cancer types, including STS." (PMID 41438985, 2025). "The suppression of MYC induces cellular senescence in different types of cancer cells, including osteosarcoma and hepatocellular carcinoma." (PMID 40290126, 2025). "According to existing studies on CUDC-907, downregulation of MYC protein is an early event induced by CUDC-907 therapy that restricts MYC-driven cancer growth." (PMID 40229260, 2025). "MYC, one of the most widely studied oncogenes, is frequently dysregulated in various cancers in a tissue-specific manner." (PMID 41239669, 2025). "EMOGI successfully identified diverse genetic alterations in well-established cancer genes, including APC high mutation frequency in colon cancer, TWIST1 promoter hypermethylation, and MYC copy number amplifications across multiple cancer types." (PMID 40565540, 2025). "Downregulated genes again were enriched for transcription factors, which included cancer‐related ones such as MYC, JUN and JUNB." (PMID 39508147, 2025). "N‐MYC enhancer invasion in NB recapitulates the c‐MYC enhancer invasion observed in cancers with elevated expression of c‐MYC." (PMID 39119816, 2025). "MYC activation can occur via various genetic, epistatic, epigenetic, and post-translational mechanisms, with nuances observed across different cancer types." (PMID 40227591, 2025). "MYC, one of the cancer reversion targets identified in our study, is a well‐established key regulator in cell fate determination." (PMID 39840939, 2025). "The mechanisms of MYC dysregulation, including gene amplification and translocation, are activated by several key signaling pathways in cancer, such as the PI3K and RAS pathways." (PMID 40732268, 2025). "One of the mechanisms by which MYC promotes cancer formation/progression is by promoting immune evasion." (PMID 39875774, 2025). "Future studies are needed to further explore the mechanisms of action of MYC in different cancer types in order to provide new targets and strategies for cancer treatment." (PMID 40290723, 2025). "Mutant EGFR and KRAS both indirectly regulate cancer metabolism by activating downstream signaling pathways for metabolic regulation including Akt, MYC, and mTORC1, which in turn regulate practically every metabolic pathway in the cell." (PMID 39796781, 2025). "On the other hand, MYC promotes cancer cell proliferation and inhibits apoptosis by regulating multiple components of the PI3K/AKT/mTOR pathway." (PMID 40717965, 2025). "Like EGFR and RAS, MYC is a viable target for pharmacological modulation, offering promising therapeutic options for cancer treatment." (PMID 39858030, 2025). "The critical role played by CDK9 in facilitating RNA Pol II transcriptional elongation makes CDK9 inhibitors well suited for the treatment of cancers characterized by transcriptional dysregulation as a consequence of MYC amplification or MLL1 rearrangements." (PMID 41360777, 2025). "Results included known cancer driver genes on eccDNA were identified, such as MYC, EGFR, CCND1 and MDM2." (PMID 40478912, 2025). "The Warburg effect, a shift to aerobic glycolysis, is a key metabolic adaptation in MYC-driven cancers, where cells increase glucose uptake and conversion to lactate even in the presence of oxygen." (PMID 41180747, 2025). "The role of CDK12/13 as oncogenes in a MYC-overexpressed context has been highlighted in other cancer models." (PMID 39533070, 2025).